HK3 (hexokinase 3)
Description:
Catalyzes the phosphorylation of hexose, such as D-glucose and D-fructose, to hexose 6-phosphate (D-glucose 6-phosphate and D-fructose 6-phosphate, respectively). Mediates the initial step of glycolysis by catalyzing phosphorylation of D-glucose to D-glucose 6-phosphate.
Synonyms: HKIII; HXK3
Tractability: Small molecule: a structure with a bound ligand is known; it has a high-quality binding pocket. Antibody: its Gene Ontology location is reachable by antibodies, with high confidence. PROTAC: ubiquitination databases record sites on it; its protein half-life has been measured.
Target class: Enzyme
Gene: Protein-coding gene on chromosome 5 (176,880,820 to 176,899,437, reverse strand). Ensembl gene ENSG00000160883.
Pathways (Reactome):
Immune System: Neutrophil degranulation
Metabolism: Glycolysis
Gene Ontology:
Molecular function: glucokinase activity; hexokinase activity; protein binding; fructokinase activity; mannokinase activity; ATP binding; D-glucose binding
Biological process: canonical glycolysis; fructose 6-phosphate metabolic process; glucose 6-phosphate metabolic process; glucose metabolic process; glycolytic process; carbohydrate derivative metabolic process; carbohydrate metabolic process; hexose metabolic process; intracellular glucose homeostasis; organophosphate metabolic process
Cellular component: cytosol; extracellular region; ficolin-1-rich granule lumen; secretory granule lumen
Genetic constraint (gnomAD): Loss-of-function variants: 98 observed, 94.68 expected, observed/expected ratio (o/e) 1.04, 90% interval 0.88 to 1.22. The upper end of that interval is the gene's LOEUF score, 1.22, which puts it in group 5 of 6, group 1 being the genes least tolerant of losing a copy. Missense variants: 1,235 observed, 1,276 expected, observed/expected ratio (o/e) 0.97, 90% interval 0.92 to 1.01. Synonymous variants: 519 observed, 529.96 expected, observed/expected ratio (o/e) 0.98, 90% interval 0.91 to 1.05.
Homologues: Orthologues: chimpanzee HK3 (99% identical), macaque HK3 (96% identical), dog HK3 (90% identical), rabbit HK3 (87% identical), pig HK3 (86% identical), mouse Hk3 (85% identical), rat Hk3 (85% identical), guinea pig HK3 (83% identical), tropical clawed frog hk2 (55% identical). Paralogues in human: HK2 (55% identical), HKDC1 (52% identical), HK1 (52% identical), GCK (26% identical).
Diseases named in the same sentence as HK3 in open-access papers:
HK3 is named in the same sentence as 55 diseases in open-access papers, as found by Europe PMC text mining. Sharing a sentence is not in itself a finding about the gene and the disease. The quoted sentences say what the papers report.
colorectal cancer (16 papers, 2016 to 2023). A primary or metastatic malignant neoplasm that affects the colon or rectum. "Previous studies found that HK3 plays a major role in acute promyelocytic leukemia and colorectal cancer, while the underlying mechanism and its role in TME remains to be elucidated 32-34." (PMID 34239350, 2021). "In colorectal cancer, HK3 overexpression was associated with epithelial-mesenchymal transition." (PMID 35154316, 2022). "HK3 encodes hexokinase 3, upregulation of which is associated with epithelial-mesenchymal transition and may be a metabolic adaptation for colorectal cancer progression." (PMID 32737333, 2020). "The association of HK3 with important EMT inducers may indicate its involvement in EMT in colorectal cancer." (PMID 29504907, 2018). "Some previous studies have revealed that HK3 can induce epithelial-mesenchymal transition in colorectal cancer." (PMID 37779195, 2023). "HK3 was also shown to promote metastasis of colorectal cancer via the nuclear factor κB/Snail/Hexokinase-3 signaling axis." (PMID 36712881, 2022). "HK3 played a functional role in acute promyelocytic leukemia, non-small lung cancer, and colorectal cancer." (PMID 33603773, 2021). "According to a recent study, HK3 has a functional role in the treatment of acute promyelocytic leukemia and colorectal cancer." (PMID 32508023, 2020). "Recently, a study established that HK3 played a functional role in acute promyelocytic leukemia and colorectal cancer." (PMID 32508023, 2020). "Previously, we have shown a frequent and significant increase in HK3 expression (more than 100-fold) in colorectal cancer." (PMID 30967137, 2019). "HK3 is closely correlated with the epithelial-mesenchymal transition in colorectal cancer and may play essential roles in the proliferation, survival, and metastases of colorectal cancer." (PMID 37106446, 2023). "HK3 is involved in epithelial-mesenchymal transition in colorectal cancer." (PMID 37779195, 2023). "HK3 is a key gene in glycolysis, and the first step of hexokinase- (HK-) catalyzed glycolysis has been confirmed to be very important in the development of colorectal cancer and melanoma." (PMID 33564363, 2021). "The inactivation of HK3 significantly affects the activation of colorectal cancer glycolysis, and then activates the downstream signaling pathways, such as apoptosis and endoplasmic reticulum stress, in colorectal cancer cells, which plays a vital role in the progression and development of cancers." (PMID 34239350, 2021). "The pre-expression of HK3 is related to the epithelial-mesenchymal transition in colorectal cancer (CRC) and maybe a strategic metabolic gene for rapid proliferation, survival, and metastasis of CRC cells." (PMID 33024640, 2020). "The purpose of the present study was to investigate the effect of silencing of hexokinase genes (HK1, HK2, and HK3) in colorectal cancer (HT-29, SW 480, HCT-15, RKO, and HCT 116) and melanoma (MDA-MB-435S and SK-MEL-28) cell lines using short hairpin RNA (shRNA) lentiviral vectors." (PMID 28105937, 2016). "Moreover, HK3 was found to prevent apoptosis in colorectal cancer and melanoma cells." (PMID 36712881, 2022). "It has been reported that the increased expression of HK3 is related to EMT in colorectal cancer, which is involved in the rapid growth and metastasis of colorectal cancer." (PMID 36072431, 2022). "The increased expression of HK3 is related to EMT in colorectal cancer, which is involved in the rapid growth and metastasis of colorectal cancer." (PMID 33564363, 2021). "In order to silence the expression of HK mRNA in colorectal cancer and melanoma cells, the cell lines were transfected with HK1, HK2, and HK3 shRNA (three shRNAs per each gene: sh#1, sh#2, and sh#3)." (PMID 28105937, 2016). "The expression levels of HK1 and HK2 were not significantly changed in both colorectal cancer and melanoma cells with HK3 knockdown." (PMID 28105937, 2016).
colorectal cancer (continued). "We observed increased expression of HK1 in colorectal cancer cells transfected by vector pLSLP-HK2, but not in melanoma ones; the mRNA and protein levels of HK3 were not altered in all cases." (PMID 28105937, 2016).
prostate carcinoma (11 papers, 2002 to 2023). A carcinoma that arises from epithelial cells of the prostate gland. "The family has 15 genes encoding secretion of serine proteases, such that from the encoding proteins, prostate-specific antigen (PSA or hK3) is an important and obvious marker for prostate cancer." (PMID 28855925, 2016). "In order to further study the role of HK3 in immunotherapy, we found high relationship between it and tumor neoantigens, especially prostate cancer and colon cancer." (PMID 34239350, 2021). "For example, invasion of MDA-MB-231 human breast cancer cells into Matrigel was suppressed by a synthetic hK1 inhibitor, and invasion of LNCaP human prostate cancer cells through Matrigel was attenuated by hK3-neutralizing antibodies." (PMID 15969748, 2005). "Prostate-specific antigen (PSA), also known as human kallikrein 3 (hK3), according to the approved new nomenclature of the human kallikrein family, is used for early detection and monitoring of prostate cancer." (PMID 12671711, 2003). "In addition, HK3 overexpression also promotes prostate cancer, acute myeloid lymphoblastic leukemia, and colon tumors." (PMID 36177003, 2022). "KLK3 gene encodes prostate-specific antigen (hK3), has been approved by the US FDA as the specific marker of prostate cancer, which is widely used for screening, diagnosing, determining the efficacy and assessing the prognosis of prostate cancer." (PMID 23587030, 2013). "This type of protease inhibitor has been reported to form complexes with the kallikrein family such as hK3 (also known as a prostate-specific antigen), hK2 and hK6, and could be applied in the diagnosis of prostate cancers." (PMID 22363757, 2012). "This suggests that hK3 enzymatic activity may promote proliferation, migration, and metastasis of prostate cancer cells." (PMID 15305183, 2004). "Prostate-specific antigen, also known as hK3, and its molecular forms are the most useful tumour markers for the prostate cancer and hK2, another member of the kallikrein gene family, may help in reducing the number of unnecessary biopsies." (PMID 12671711, 2003). "PSA, also known as human kallikrein 3 (hK3 or KLK3), is one of the earliest discovered serological prostate cancer (PC) indicators widely used in clinical interpretation of prostate cancer." (PMID 36832253, 2023). "The switch from HK2 to HK3 mediated glucose conversion in cancer cells is also interesting in this respect, since HK2 is important in mediating the Warburg effect in prostate cancer." (PMID 36282866, 2022). "Of them, kallikrein 3 (hK3), or more commonly named as prostate-specific antigen (PSA), has gained prominence as the most valuable tumour marker and is currently used widely for the diagnosis, monitoring, and population screening for prostate cancer." (PMID 15305183, 2004). "According to a study conducted by Rehault, hK2 and hK3 could represent important regulators of insulin-like growth factors (IGFs) in the proliferation of prostate cancer cells; however, similar findings have not been published on EOC." (PMID 15969748, 2005).
Sepsis (10 papers, 2021 to 2026). Sepsis is defined as life-threatening organ dysfunction caused by a dysregulated host response to infection. "Receiver operating characteristic (ROC) curve analysis demonstrated that HK3, as a novel metabolic checkpoint, serves as an excellent diagnostic biomarker for sepsis." (PMID 41964014, 2026). "HK3 has been identified as a key biomarker for pediatric sepsis and septic shock and exhibits good diagnostic value." (PMID 40177399, 2025). "A recent study also indicated that HK3 was a diagnostic marker and had potential functions in pediatric sepsis." (PMID 40821971, 2025). "Unexpectedly, the prognosis of sepsis was significantly associated with four of the five hub genes: HK3, GPR84, CLEC4D, and S100A12." (PMID 40821971, 2025). "Single-cell RNA sequencing analysis demonstrated a significant increase in HK3 expression in monocytes from the sepsis group compared to the control group." (PMID 41964014, 2026). "Through analysis of the GEO database, we found that HK3 is significantly elevated in the peripheral blood of sepsis patients." (PMID 41964014, 2026). "Using an LPS-induced monocyte sepsis model, we found that HK3 boosts glycolytic activity and lactate accumulation." (PMID 41964014, 2026). "Our findings not only establish HK3 as a key metabolic regulator in sepsis but also elucidate its molecular mechanism in driving excessive monocyte-mediated inflammation." (PMID 41964014, 2026). "This study identified four hub genes (CLEC4D, GPR84, S100A12, and HK3) with significant prognostic value in sepsis and predicted a ceRNA network (NEAT1-hsa-miR-495-3p-ELF1) regulating their expression." (PMID 40821971, 2025). "In a sepsis-induced acute model, HK3 knockdown significantly inhibits cell proliferation, promotes inflammation, increases apoptosis, and blocks glycolysis." (PMID 40177399, 2025). "The glycolysis-encoding genes HK2 (hexokinase-2), HK3 (hexokinase-3), LDHA, and PKM (pyruvate kinase M) in the PMNs of patients with sepsis were significantly altered compared to those in the PMNs of healthy volunteers." (PMID 35090526, 2022). "The activity of HK3 increased rapidly after lipopolysaccharide (LPS) exposure, and the up-regulation of HK3 in sepsis was an important factor to interrupt energy production and cause AKI." (PMID 33949285, 2021). "Notably, targeted HK3 knockdown effectively suppressed this pro-inflammatory cascade, highlighting its critical role in sepsis pathogenesis." (PMID 41964014, 2026). "Moreover, we identify HK3 as a promising therapeutic target for mitigating hyperinflammatory responses in sepsis." (PMID 41964014, 2026). "Tier 2 sepGIKs included 89 sepGIKs (399 pairs), such as FFAR2 (free fatty acid receptor 2), CCR7 (C-C chemokine receptor type 7), HK3 (hexokinase 3), and IRAK3 (interleukin-1 receptor-associated kinase 3), which were differentially expressed in at least 14 sepsis datasets." (PMID 40761792, 2025). "Conversely, the expression of genes encoding enzymes involved in glycolysis and lactate metabolism and the synthesis of membrane transporters, i.e., glucose transporter (GLUT-1), hexokinase-3, PKM2, subunit A of LDH, and MCT4, are significantly increased in patients with sepsis." (PMID 34445236, 2021).
acute promyelocytic leukemia (7 papers, 2018 to 2022). An aggressive form of acute myeloid leukemia (AML), characterized by arrest of leukocyte differentiation at the promyelocyte stage, due to a specific chromosomal translocation t(15;17) in myeloid cells. "Downregulation of HK3 expression impaired neutrophil differentiation and increased sensitivity to anthracyclines in acute promyelocytic leukemia." (PMID 36712881, 2022). "Our group previously identified HK3 as a transcriptional target of the hematopoietic transcription factor PU.1 (SPI1) during acute promyelocytic leukemia (APL) differentiation." (PMID 35538058, 2022). "A recent study found that HK3 plays an important role in acute promyelocytic leukemia." (PMID 33221754, 2020). "A recent study reported functional role of HK3 in acute promyelocytic leukemia." (PMID 29504907, 2018).
breast carcinoma (7 papers, 2002 to 2025). "For luminal A breast cancer, we observed that genes associated with favourable prognosis—including key regulators of glucose metabolism HK3, LDHAL6A, apoptosis regulator PRKCB, and alcohol dehydrogenase ADH6—are not directly targeted by current treatments." (PMID 41007296, 2025). "HK3 is a very well-known glycolysis gene whose overexpression could be linked to hypoxia-induced upregulation of glycolysis and improvement in breast cancer cell survival." (PMID 33024640, 2020). "The prognostic value of KLK15 is similar to that of hK3 (PSA) which is also an independent marker of favourable prognosis in breast cancer." (PMID 12439720, 2002). "The expression of glycolytic enzymes, including HK3, was also increased in breast cancer, and HK3 was considered to be the most important gene in pediatric acute lymphoblastic leukemia; it plays an important role in the prognosis of the disease through the glycolytic pathway." (PMID 33564363, 2021). "The potential prognostic importance of hK3 expression in breast cancer has also been reported." (PMID 14710225, 2004).
non-small cell lung carcinoma (5 papers, 2021 to 2024). A group of at least three distinct histological types of lung cancer, including non-small cell squamous cell carcinoma, adenocarcinoma, and large cell carcinoma. "HK3 was associated with the inflammatory response in non-small cell lung cancer and predicted anti-PD1 immunotherapy." (PMID 36494582, 2023). "HK3 is correlated with immune infiltrates and predicts response to immunotherapy in non-small cell lung cancer." (PMID 38714539, 2024). "In non-small cell lung cancer, HK3 expression correlates with immune cell infiltration and tumor sensitivity to Pembrolizumab." (PMID 36177003, 2022). "HK3 is also correlated with immune infiltrates and can predict immunotherapy response in non-small cell lung cancer." (PMID 33816274, 2021). "In recent years, a study demonstrated that HK3 expression was assoiated with immune cell infiltration and could predict the response to immunotherapy in non-small cell lung cancer." (PMID 37779195, 2023). "Moreover, HK3 expression is correlated with immune cell infiltration in non-small cell lung cancer and clear cell renal cell carcinoma." (PMID 37779195, 2023).
acute myeloid leukemia (4 papers, 2022 to 2024). Acute myeloid leukemia (AML) is a group of neoplasms arising from precursor cells committed to the myeloid cell-line differentiation. "While HK1 and HK2 are ubiquitously expressed, the less well-studied HK3 is primarily expressed in hematopoietic cells and tissues and is highly upregulated during terminal differentiation of some acute myeloid leukemia (AML) cell line models." (PMID 35538058, 2022). "We have previously reported on the upregulation of HK3 during terminal differentiation of selected acute myeloid leukemia cell lines, specifically during ATRA-induced neutrophil-like differentiation of acute promyelocytic cells." (PMID 35538058, 2022). "Recently, a direct interaction between BIM and Hexokinase 3 (HK3) could be demonstrated in acute myeloid leukemia (AML) cells." (PMID 40150937, 2024).
clear cell renal cell carcinoma (4 papers, 2021 to 2023). "HK3 belongs to the hexokinase (HK) family and is suggested playing oncogenic roles in various cancers, and promotes proliferation and decreases apoptosis of clear cell renal cell carcinoma cells." (PMID 37106446, 2023). "HK3 was also identified as a biomarker of macrophages in clear cell renal cell carcinoma." (PMID 36712881, 2022).
glioblastoma (4 papers, 2017 to 2024). The most malignant astrocytic tumor (WHO grade IV). "The expression level of HK3 was significantly elevated along with the tumor grade and was the highest in glioblastoma (GBM, grade 4)." (PMID 37779195, 2023). "High expression of HK2 was significant in IDH1WT LGG, whereas HK3 expression was significant higher in IDH1WT glioblastoma." (PMID 28467784, 2017). "To investigate the biological role of HK3 in glioma, we performed bioinformatics analysis and established a mouse glioblastoma (GBM) xenograft model." (PMID 37779195, 2023). "However, there is a need for in-depth characterization of the role of HK3 in glioblastoma multiforme (GBM)." (PMID 36712881, 2022).
renal carcinoma (4 papers, 2021 to 2024). A carcinoma arising from the epithelium of the renal parenchyma or the renal pelvis. "The second protein, a member of the hexokinase family encoded by Hk3, participates in tumor immune microenvironment remodeling and promotes immune escape, with its high expression leading to a poor prognosis in patients with renal carcinoma." (PMID 36430209, 2022). "Compared to the normal cell line, all three renal cancer cell lines exhibited higher levels of HK3 expression, mirroring the elevated HK3 expression observed in clinical tumor tissues." (PMID 39179546, 2024). "The high expression of HK3, ENO2, ENO3, and PSAT1 indicated a short OS and a high risk of developing renal cancer." (PMID 33564363, 2021). "Initially, we analyzed the expression levels of HK3 in renal cell lines, including one normal renal cell line (HK2) and three renal cancer cell lines (786-O, Caki-1, and ACHN)." (PMID 39179546, 2024).